CASP9 (caspase 9)
Diseases named in the same sentence as CASP9 in open-access papers (continued):
Sharing a sentence is not in itself a finding about the gene and the disease.
tumor (continued). "VSV-S expressed a high level of Smac to replenish the endogenous Smac and induced elevated apoptosis via the caspase-9 pathway and strong tumor necrosis in a human breast cancer model in nude mice, and inhibition of tumor growth in the syngeneic mouse model." (PMID 35197076, 2022). "We also found that cleavage-activated Caspase-9 increased in tumor tissues treated with JND4135 at a dose of 20 and 40 mg/kg." (PMID 36235036, 2022). "Compound 29e showed the most potent tumour cell growth inhibitory activity towards K562 and induced its apoptosis with the expression change of apoptosis-related protein including caspase-3, caspase-9 and PARP." (PMID 35109719, 2022). "According to our analytical results, CASP4, CASP5, and CASP9 were upregulated in the tumor tissues, and their high expression indicated poor survival rate." (PMID 35153782, 2022). "Studies have shown that tumor cells suppress radiation-induced immunity by hijacking caspase-9 signaling." (PMID 35846123, 2022). "The tumor tissues collected from mice that received the combination of Cqn and Utt-B exhibited strong cleavage of caspase 9 mother band and PARP." (PMID 35211405, 2022). "These treatments also increased the expression of cleaved caspase-9 and cleaved caspase-3, and DNA damage in tumours." (PMID 35236377, 2022). "BA treatment leads to the production of ROS, which results in the reduction of mitochondrial potential and pro-apoptotic proteins, such as Caspase-3 and Caspase-9, become up-regulated and induce apoptosis of tumor cells." (PMID 36611970, 2022). "These treatments also increased significantly the level of cleaved caspase-9 and cleaved caspase-3 in tumour tissues." (PMID 35236377, 2022). "Knockdown or downregulation of PIM-1 was shown to inhibit tumor proliferation and induce mitochondria-mediated apoptosis by activating caspase-9." (PMID 36687624, 2022). "Then the levels of IFN-γ, IL-10 and caspase-9, and also the tumor size in mice receiving anti-IL-10-added vaccines were compared with those of mice treated with isotype homologs six weeks after tumor challenge." (PMID 35752792, 2022). "Multiple studies have suggested that decreased Bcl-2/Bax ratio in tumor cells triggers activation of caspase-9/-3 and subsequently promotes the mitochondrial-mediated apoptosis." (PMID 36387351, 2022). "The expression of cleaved caspase-9 was significantly higher in tumor tissues derived from the MG731, MG5200, and 3Mix-3 groups than in the control group." (PMID 36077182, 2022). "For example, previous studies have found that tumor cells can hijack caspase-9 signaling to suppress radiation-induced immunity." (PMID 36675746, 2022). "The expression levels of CCND1, VEGFA, AURKB, HDAC1, HSP90AA1, and HSP90AB1 were positively correlated with immune cell infiltration levels, whereas the expression levels of SIRT2 and CASP9 were negatively correlated with the tumor purity of BRCA." (PMID 35845599, 2022). "DEK silencing induces apoptosis of tumor cells by activation of caspase-9 and subsequent cleavage and activation of procaspase-3, which then cleaves different cellular endogenous substrates leading to cell death." (PMID 35769815, 2022).
tumor (continued). "These three treatments also resulted in a significantly higher expression of cleaved caspase-9 in tumours with an increase of 85.2% (P < 0.001), 68.4% (P < 0.001), and 21.3% (P < 0.05), respectively." (PMID 35236377, 2022). "Apoptotic pathways play an important role in tumorigenesis, and our results indicate that pro-apoptotic BAD and cleaved caspase 9 were enriched in tumor cells of unmatched nodal metastases." (PMID 35651606, 2022). "The ratios of cleaved caspase-9 to caspase-9 in tumor tissues derived from all treatment groups were significantly higher than those in the control group, whereas those of caspase-8 differed little among all groups." (PMID 35336106, 2022). "In this study, expression levels of BAX, Caspase-3, Caspase-9, and cleaved Caspase-3 in the blood and tumor tissues of BGC-823-bearing nude mice were increased, while Bcl-2 expression was relatively low." (PMID 36438804, 2022). "TRAIL and caspase-9 in the tumor microenvironment were measured to investigate the mechanism through which our developed adjuvant vaccine destroys tumor cells." (PMID 35752792, 2022). "Similar to the results of cell cultures, the activities of caspase-9 and caspase-3 were significantly enhanced in iturin A-treated tumor tissues, while activities in control groups were relatively lower." (PMID 33970365, 2021). "There is evidence that caspase 9 (CASP9) signaling hijacked by the irradiated tumor cells can result in acquired resistance to radiation by the inhibition of innate DNA sensing." (PMID 33928081, 2021). "At the same time, hirsutine treatment also elevated caspase-3 and caspase-9 mRNA levels, suggesting that hirsutine has a potential antitumor activity, thus enlightening the use of phytomedicines in tumor therapy." (PMID 33604171, 2021). "A combination of CASP9 overexpression with radiation has shown promise in enhancing the efficacy of tumor treatment." (PMID 34485134, 2021). "Nano-β-TCP induced apoptosis of tumor cells by the apoptotic signalling that resulted in overexpression of Bax, caspase-3, and caspase-9." (PMID 33628375, 2021). "Three apoptotic markers included general apoptosis protein-activated caspase-3, extrinsic apoptosis protein-activated caspase-8, and intrinsic apoptosis protein-activated caspase-9 in the tumor section were all markedly increased by imipramine and erlotinib." (PMID 34765548, 2021). "Caspase-9 can suppress tumor growth by triggering intrinsic apoptosis in response to cellular damage such as genomic instability, oxidative stress, and aberrant proliferation." (PMID 34305609, 2021). "By immunoblot analysis, our data showed a decreased expression level of LC3-II with an increased level of SQSTM1, cleaved PARP, and caspase 9/3 in tumor of T-DM1 combined with LY294002 group versus T-DM1-treated group." (PMID 33731670, 2021). "It is already known that CDKN1A, BAX, CASP9 and E-cadherine are involved in tumor growth suppression and apoptosis." (PMID 34281228, 2021). "For example, the mRNA expression of CASP9 was down-regulated in tumor tissue compared to marginal tissue, and ITGB3, involved in reactive oxygen species-induced migration and invasion processes, is known to be a malignant indicator in CRC." (PMID 33692961, 2021). "According to the results of this study, aerobic training has increased the gene expression of cytochrome C, Apaf-1, caspase-3, and caspase-9 in tumor tissue." (PMID 35083006, 2021). "The expression levels of proteins related to apoptotic cell death, including Bcl-2, Bax, cleaved caspase-3, and cleaved caspase-9 in the tumor tissues was also consistent with the results in vitro." (PMID 32606352, 2020). "The results also illustrated that NDV-HA2 treatment significantly induced the expression of caspase-9 in tumor lysate in comparison to NDV-treated mice (P < 0.01)." (PMID 32782438, 2020).
tumor (continued). "The results confirmed that 125I treatment induced tumor cell apoptosis, with decreasing P21, Ki-67, survivin, livin level expression, increased Caspase-9 expression and elevated caspase-3 activation." (PMID 33059701, 2020). "Given their similar characteristics, Bax, p73, Casp-9 and Bcl-2 have been classified as biomarkers for promotion of tumor apoptosis (BPAs) in this study." (PMID 32993581, 2020). "VP also induced tumor cell apoptosis, and promoted the cleavage of Caspase-9 and PARP in the cells of various molecular subtypes of BC." (PMID 33121449, 2020). "Following IR treatment, caspase 9 was identified as a potent inhibitor of type I IFN production by tumor cells, which reduced succeeding antitumor T cell responses and the overall efficacy of IR." (PMID 33238631, 2020). "Western blot analysis showed that combination treatment leads to substantial changes in the proteins involved in caspase-mediated apoptosis of tumor cells, in particular, caspase-3, caspase-8 and caspase-9 cleavage and subsequent PARP cleavage." (PMID 32019988, 2020). "Taken together, these results indicated that caspase-9/caspase-3/GSDME axis contributed to CAP-induced tumor cell pyroptosis." (PMID 32341339, 2020). "WB analysis showed that costunolide increased the expression of cleaved caspase 9, cleaved caspase 3 and Bax proteins and decreased the expression of Bcl-2 protein in xenografted tumor." (PMID 31242894, 2019). "The anti-tumour mechanism of drug-drug combination is to induce apoptosis through up-regulating the activity of caspase-3 and caspase-9 by inhibiting the activity of bcl-2." (PMID 30872765, 2019). "Increase in Annexin V staining and expression of caspase 9 by miR-101-3p point to activation of intrinsic apoptotic pathway as one of the tumor suppressor mechanisms in HCT116, corroborating previous studies." (PMID 31864341, 2019). "Marsdenia tenacissima induced apoptosis in tumor cells by regulating the Caspase 3, Caspase 9, Bak, Bax, Bcl-xl, Bcl-2, Fas, and PKC genes, as well as the PI3K/AKT/mTOR and the Hippo signaling pathways." (PMID 31341493, 2019). "Subsequently, the correlation analysis between ceRNAs and tumor-infiltrating immune cells discovered that both CASP9 and RASSF8-AS1 were positively correlated with Dendritic cells activated." (PMID 31681739, 2019). "Costunolide increased the expression of cleaved caspase 9, cleaved caspase 3 and Bax proteins and decreased the expression of Bcl-2 protein in xenografted tumor." (PMID 31242894, 2019). "In all tumor cell lines, NDV infection led to the loss of mitochondrial membrane and activation of caspase 9, highlighting the importance of the intrinsic pathway in activation of NDV-mediated apoptosis." (PMID 32489950, 2019). "Triptolide increased the expression of associated apoptotic proteins (cleaved PARP1, cleaved caspase-3, and cleaved caspase-9) in tumor tissues." (PMID 30111354, 2018). "Emetine, an inhibitor of protein synthesis, was shown to be able to regulate the alternative splicing of Bcl-x and Caspase 9 in tumor cells." (PMID 29788973, 2018). "In this study, the expression of Bcl-2, Bax, caspase-3, caspase-8 and caspase-9 in tumor tissues were detected by western blotting, and the cell cycle makers and apoptotic index of tumor cells were detected by flow cytometry." (PMID 30670974, 2018). "Changes in the pro-apoptotic marker caspase 9 are in line with the observed tumor size reduction in mice bearing WM1366 tumors using the combinatorial treatment." (PMID 30405888, 2018). "Accumulating evidence has shown the role of the PI3K/Akt pathway in the mechanisms of EPS8 associated tumor proliferation, survival and drug resistance by activating downstream targets, such as FOXM1, mTOR, MMP-9 and caspase-9." (PMID 29357910, 2018). "RPR-induced K562 tumor cells developed apoptosis because caspase-3 mRNA and caspase-9 mRNA were increased." (PMID 29688864, 2018).
tumor (continued). "A suicide gene, inducible caspase 9 (iCasp9) was integrated to CAR construction to regulate the persistence of CAR T-cells to control the on-target/off-tumor toxicities." (PMID 30257649, 2018). "This vector enabled enhanced tumor cell apoptosis through activation of the caspase-9/PARP pathway, which ultimately resulted in reduced cisplatin doses." (PMID 29534501, 2018). "The results showed that EAEO treatment significantly enhanced apoptotic nucleus in the tumor sections, suppressed the ratio of Bcl-2/Bax and increased the expression of cleaved caspase-9 and -3." (PMID 29867489, 2018). "The data indicated that AG induced apoptosis in tumor cells via the activation of caspase-9/caspase-3 and the inhibition of NF-κB/p65." (PMID 28199969, 2017). "Our study showed that dA increased the activation of caspase-9/3 and PARP, upregulated the Bax/Bcl-2 ratio, and caused DNA damage, suggesting that the tumour death trigged by dA was related to mitochondria associated apoptotic pathway." (PMID 28775302, 2017). "Wilcoxon signed-rank test indicated that the protein levels of cleaved caspase-3, caspase-3, caspase-8, and caspase-9 in tumor tissues were significantly higher compared to those in adjacent normal tissues (all p<0.001)." (PMID 28700659, 2017). "The activation of Akt by PI3K attenuates apoptosis and facilitates tumor cell growth via phosphorylation to inhibit various downstream targets, including the pro-apoptotic Bad, Bax, and caspase-9, as well as transcription factors and other protein kinases." (PMID 29311937, 2017). "The relative mRNA expression of Caspase-3 and Caspase-9 of mice tumor tissues was highest in cinobufagin + CDDP group followed by CDDP alone, cinobufagin alone, and vehicle in that order." (PMID 29156710, 2017). "On mitochondrial apoptosis pathway, our data indicated that GSC induced tumor cell apoptosis by activating caspase-9, -3, led to PARP cleavage and inhibited NF-κB/p65." (PMID 29379440, 2017). "The expression levels of cleaved caspase-3, caspase-3, caspase-8, and caspase-9 in tumor and adjacent normal cells in patients were further scored." (PMID 28700659, 2017). "The comparisons of cleaved caspase-3 (CC-3), caspase-3 (C-3), caspase-8 (C-8) and caspase-9 (C-9) expression in the tumor and tumor adjacent normal tissues of OTSCC patients." (PMID 28700659, 2017). "A high level of caspase-9 was correlated with female patients (p = 0.019), while expression level of caspase-9 was higher in tumor tissues with poor cell differentiation compared to those with well or moderate cell differentiation (p = 0.007)." (PMID 28700659, 2017). "Further determination of the expression of apoptotic and autophagic proteins in the xenograft of tumor tissues showed that overexpressing miR-125b impaired 5-FU induced expression of apoptotic proteins Bax, cleaved caspase-3, caspase-9 and cleaved PARP." (PMID 28176874, 2017). "Apoptotic protease activating factor-1 (Apaf-1), of Caspase-9 apoptotic pathway, is a tumor suppressor gene." (PMID 28479926, 2017). "Consistently, decreased Bcl-2 expression, increased cytochrome c and PARP level, and activated caspase-3 and caspase-9 were observed in the tumor samples." (PMID 28567017, 2017). "A reduction in Apaf-1 occurs during tumor progression from primary to systemic metastasis and can contribute to the ability of tumor cells to evade Caspase-9 apoptotic pathway." (PMID 28399853, 2017).
tumor (continued). "We genotyped 7 potentially functional polymorphisms in CASP3, CASP7, CASP8, CASP9, CASP10 genes in 362 HCC patients of receiving surgical resection of HCC tumor." (PMID 28453560, 2017). "As a possible control for chloramphenicol, rotenone induced increases in the abundance of Cytc, cleaved caspase 9 and cleaved caspase 3 in tumor cells." (PMID 27437770, 2016). "As the promoter of the apoptotic pathway and the Caspases family, caspase-9 plays an important role in the development of tumours, inactivated caspase-9 has been detected in several human tissues such as in heart, testis and ovary." (PMID 27377320, 2016). "Western blot analysis suggested that chloramphenicol (≥ 50 μg/mL) increased the abundance of Cytc, cleaved caspase 9, and cleaved caspase 3 in tumor cells, and that this effect on the caspases was blocked by 25 μM Z-VAD-FMK, a nonspecific caspase inhibitor." (PMID 27437770, 2016). "We observed increased expression of caspase-3 and caspase-9 and their transcripts in tumor tissues from mice injected subcutaneously with HCMV-infected HepG2 cells, but not from the control groups." (PMID 27626063, 2016). "And one mechanism for many therapeutic drugs was to induce tumor cell apoptosis by caspase-8-regulated plasma membrane extrinsic pathway or caspase-9-regulated cell damage intrinsic pathway." (PMID 27015938, 2016). "In agreement with the IHC results, we observed increased expression of caspase-9 and caspase-3 in tumor tissue from mice injected subcutaneously with HCMV-infected HepG2 cells but not from the control groups using western blotting." (PMID 27626063, 2016). "Western Blot analysis were used to investigate the crucial molecules involved in selected signaling pathways associated with apoptosis (caspase-9 and PARP-1), cell survival (ERK 1/2) and tumor progression (Wnt3a and β-catenin)." (PMID 27367907, 2016). "In particular, in silenced MCF-7 cells we found a higher levels of well-known pro-apoptotic factors such as BAD and Caspase-9 and of Col18, that acts as an endogenous inhibitor of tumor growth and angiogenesis." (PMID 26799588, 2016). "We observed that several HepG2 cells were positive for both caspase-9 and caspase-3 in tumor biopsies from mice injected subcutaneously with HCMV-infected HepG2 cells." (PMID 27626063, 2016). "Smac, as a novel tumor suppressor, exerts anti-tumor activity via the cytochrome c/Apaf-1/caspase-9 pathway." (PMID 27552933, 2016). "Our results in xenografted tumor demonstrated that NVP-BEZ-235 and NVP-LDE-225 acted in a co-operative manner to inhibit tumor growth and induce cleavage of caspase-3 and caspase-9." (PMID 26451606, 2015). "Taken all, the use of PEGylated FA-MTX-MNPs can activate the tumor suppressor genes Bax and Caspase 9, but inactivate the tumor inducer gene AKt, which triggers the apoptosis pathway(s)." (PMID 25880772, 2015). "Cleavage of caspase-3 and caspase-9 by these drugs would indicate the induction of apoptosis in tumor tissues." (PMID 26451606, 2015). "Similar results were obtained in the placebo group, with the exception of one tumor with more than 10% of caspase 9-positive cells (casp9I was from 2.80 to 10.80% with the mean 6.14 ± 0.49)." (PMID 25852394, 2015). "In the case of caspase 9, these are uncommon, and it is the abrogation of post mitochondrial functional activities that favor tumor progression." (PMID 26606169, 2015).